KRAS (KRas proto-oncogene, GTPase)
Diseases named in the same sentence as KRAS in open-access papers (continued):
Sharing a sentence is not in itself a finding about the gene and the disease.
colorectal cancer (continued). "This study aimed to characterize the ATP-synthesis by oxidative phosphorylation in colorectal cancer (CRC) and premalignant colon polyps in relation to molecular biomarkers KRAS and BRAF." (PMID 32231083, 2020). "Selective covalent inhibitors of the KRAS G12C mutant, such as AMG 510, elicited promising results in clinical trials for the treatment of lung and colorectal cancers." (PMID 31878223, 2019). "Meanwhile, exclusive generation of intracellular free radicals, such as hydrogen peroxide (H2O2) and superoxide (O2−), through the oxidation of antioxidants induces apoptotic cell death in KRAS and BRAF mutant colorectal cancer." (PMID 30903981, 2019). "Finally, using DNA mass spectrometry to evaluate a panel of colorectal cancer hotspot mutations present in the ACF, we found that three APC gene mutations were positively associated with the presence of Instestinibacter sp., whereas KRAS mutations were positively correlated with Ruminococcus gnavus." (PMID 31754633, 2019). "For example, high levels of vitamin C can selectively kill KRAS- and BRAF-driven colorectal cancer cells by inducing oxidative stress, suppressing glycolysis and the subsequent energy crisis." (PMID 30688660, 2019). "A post-progression tumour biopsy was obtained in one patient with KRAS mutant, MSS colorectal cancer who progressed after 12 cycles at 48 mg." (PMID 31303643, 2019). "KRAS is seen as a high accuracy marker for PDAC, though has also been detected in the ctDNA of colorectal cancer patients." (PMID 31608239, 2019). "Only three biomarker-drug-tumour combinations had both types of responses: the triplets ‘BRAF V600E-panitumumab, trametinib-colorectal cancer’, ‘EGFR R451C-cetuximab-colorectal cancer’ and ‘KRAS G13D-cetuximab-colorectal cancer’." (PMID 31169290, 2019). "Taken together, these findings suggest that overactivation of Akt contributes to MEK inhibitor resistance in KRAS and BRAF mutant colorectal cancer." (PMID 31769426, 2019). "KRAS and BRAF are two major oncogenic drivers of colorectal cancer (CRC) that have been frequently described as mutually exclusive, thus the BRAF V600E mutation is not expected to be present in the cases with KRAS mutation." (PMID 29127628, 2019). "This system defines about 50 genomic tests with sufficient evidence for clinical implementation (e.g., KRAS and human epidermal growth factor receptor 2 (HER2) tests to inform use of cetuximab in colorectal cancer and lapatinib in breast cancer, respectively)." (PMID 29772692, 2018). "The aim of this study was to validate a molecular classification of colorectal cancer (CRC) based on microsatellite instability (MSI), CpG island methylator phenotype (CIMP) status, BRAF, and KRAS and investigate each subtype’s response to chemotherapy." (PMID 30188916, 2018). "A connection between this phenomenon and the upregulation of GLUT1 in KRAS and BRAF mutant cells was recently proposed to account for the anti-tumor activity of ascorbate in colorectal cancer." (PMID 30018566, 2018).
colorectal cancer (continued). "In patients with metastasized colorectal cancer (CRC), cfDNA testing for Kirsten rat sarcoma viral oncogene homolog (KRAS) and neuroblastoma rat sarcoma viral oncogene homolog (NRAS) mutations also holds prognostic value." (PMID 30092778, 2018). "C19 showed high cytotoxicity in the colorectal cancer cell lines HCT116 and LoVo, with a stronger effect in KRAS-dependent LoVo cells." (PMID 30382908, 2018). "The molecular characterization of colorectal cancers provided evidence that about 2% of these patients at all stages display HER2 overexpression and 5% among KRAS-WT metastatic patients." (PMID 29652830, 2018). "Other studies recently showed that vitamin C selectively killed KRAS and BRAF mutant colorectal cancer cells by targeting glyceraldehyde-3-phosphate dehydrogenase (GAPDH)." (PMID 30005692, 2018). "miR-1298 acts a tumor suppressor in KRAS-driven NSCLC and colorectal cancer cells by directly targeting the mRNA of both FAK and the Laminin subunit beta 3 (LAMB3), lowering their protein expression levels." (PMID 29891810, 2018). "We applied this DTBP platform to compare analyzed plasma with analyzed tumor tissue performed by KRAS and BRAF testing in 14 prospective colorectal cancer (CRC) patients (stages I–IV) and in 10 healthy controls." (PMID 30356899, 2018). "It is also involved in activated KRAS-mediated transcriptional activation of USP28 and binds to the USP28 promoter in colorectal cancer cells." (PMID 29568375, 2018). "In addition, to further elucidate whether the altered expression of the candidate miRNAs occurred in a BRAF-dependent fashion, we added KRAS-mutant colorectal cancers (n = 20) to the qRT-PCR and compared the miRNA expressions between BRAF-mutant tumors and KRAS-mutant tumors." (PMID 29115941, 2017). "The aim of the study was to evaluate the current rate of molecular testing prescription (KRAS codons 12/13, BRAF and microsatellite instability (MSI)) in newly diagnosed colorectal cancer (CRC) patients and to determine which factors influence testing." (PMID 29137623, 2017). "To investigate this, we utilized an isogenic set of KRAS‐mutant (mt) HCT116 (constitutively active KRAS) and genetically corrected WT HKh‐2 and HKe‐3 colorectal cancer lines, which exhibited similar growth rates." (PMID 28173629, 2017). "The role of vitamin C has been of interest again after a preclinical mice study showed that high-dose vitamin C is selectively lethal to KRAS and BRAF mutant colorectal cancer cells by targeting the glutathione pathway." (PMID 28791253, 2017). "Correlation between EGFR, AKT1, MYC, KRAS and SRC and, colorectal cancers separately or in combination with the other genes are studied and confirmed." (PMID 29511483, 2017). "In human cancer, a positive (+) enrichment was observed in mutant KRAS patients compared to wild-type in LAC (n=3), PDAC, colorectal cancer (CRC), cholangiocarcinoma (CCA) and multiple myeloma (MM)." (PMID 28220783, 2017). "Our results indicated that KRAS detected in cfDNA was a prognostic marker for OS and PFS of pancreatic cancer, colorectal cancer and NSCLC." (PMID 28796802, 2017). "Equally prominent were genes PIK3CA (44%) in breast, KRAS (51%) in lung, and APC (70%) in colorectal cancers." (PMID 28371134, 2017). "It was not until recently that the role of vitamin C has been of interest again after a preclinical mice study showed that high-dose vitamin C is selectively lethal to KRAS and BRAF mutant colorectal cancer cells by targeting the glutathione (GAPDH) pathway." (PMID 28791253, 2017). "Consistent with earlier studies, patients with a BRAF-mutant colorectal cancer had a poorer OS compared to those with a KRAS/BRAF-wild-type and KRAS-mutant cancer." (PMID 29115941, 2017). "Following the MTD determination, three expansion cohorts of patients with biliary cancer, KRAS-mutant colorectal cancer, and BRAF-mutant colorectal cancer were enroled to further assess the safety and clinical activity of binimetinib." (PMID 28152546, 2017).
colorectal cancer (continued). "AZD8055, an mTORC1/2 inhibitor, reduces MCL-1 expression in KRAS- and BRAF-mutant colorectal cancer cells." (PMID 28659182, 2017). "This intermittent dosing regimen was chosen based on a previously published report that describes the effectiveness of these inhibitors on KRAS-mutant and BRAF-mutant non-small lung cancer and colorectal cancer lines." (PMID 28640835, 2017). "For example, in colorectal carcinomas Ras-MAPK pathway alteration are found in the majority of tumors, with a significant pattern of mutual exclusivity of alteration in KRAS, NRAS and BRAF12." (PMID 29118384, 2017). "A higher expression of p16INK4A was observed in colorectal cancer cells expressing KRAS4AG12V, compared to those expressing KRAS4BG12V, although both cells exhibited similar levels of KRAS." (PMID 26799184, 2016). "For colorectal cancer (CRC) patients, international guidelines made RAS (KRAS and NRAS) status a prerequisite for the use of anti-epidermal growth factor receptor agents (anti-EGFR)." (PMID 27999270, 2016). "We hypothesized that KRAS mutation alone may not markedly influence colorectal cancer metabolism." (PMID 27924922, 2016). "However, our retrospective large cohort of patients seemed to identify GNAS-mutated colorectal cancer as associated with aggressive clinical course and phenotypic characteristics resembling to PMP (right side origin, mucinous histology, peritoneal involvement and concomitant KRAS mutations)." (PMID 27154293, 2016). "It is also evident that KRAS and HRAS oncogenes differentially regulate autophagic cell properties in the examined colorectal cancer cells." (PMID 26802026, 2016). "The panel allows the detection of mutations that are currently considered as actionable (NRAS, KRAS) or putatively actionable (BRAF, PIK3CA) in colorectal cancer." (PMID 26047774, 2015). "A patient with colorectal cancer with wt BRAF and wt KRAS in the primary tumor, who received a cetuximab-based combination for nearly one year had an emergence of a low frequency BRAF V600K mutation in cfDNA (0.02%)." (PMID 25980577, 2015). "The EGFR/HER2/KRAS/BRAF signaling pathway has been reported in pancreatic cancer and colorectal cancer other than in ovarian cancer." (PMID 26490766, 2015). "More recently, Qiagen received FDA approval of a therascreen® KRAS RGQ PCR kit, paired with a colorectal cancer drug." (PMID 26622475, 2015). "The study reported that HER-2 gene amplification was observed in 26.3% of KRAS and v-raf murine sarcoma viral oncogene homolog B (BRAF) wild type colorectal carcinomas in Spanish patients." (PMID 25452770, 2015). "In colorectal cancer, anti-EGFR antibodies are routinely used as second-line therapy of KRAS wild-type tumors." (PMID 24894453, 2014). "In SW620 colorectal cancer cells which express endogenous mutant KRAS, Ponatinib and AMG-47a were highly toxic at concentrations required to observe loss of EGFP-KRASG12V in HeLa cells (>1 μM), thus we were unable to test whether these compounds also affect the levels of endogenous KRAS oncoprotein." (PMID 25093678, 2014). "Nucleotide and amino acid changes in KRAS in patients with non-small cell lung carcinoma (NSCLC) and colorectal cancer (CRC)." (PMID 25158139, 2014). "In this study we evaluated KRAS and BRAF status in 159 colorectal cancer samples obtained from the University of Tirana." (PMID 25267307, 2014).
colorectal cancer (continued). "Colorectal carcinomas that are wild type for KRAS are often sensitive to EGFR blockade and therefore KRAS testing can prevent both ineffective treatment and treatment-associated toxicity." (PMID 24676216, 2014). "Numerous signaling cascades including KRAS/BRAF and PI3K/AKT were certified to entangle in colorectal cancer." (PMID 23825635, 2013). "KRAS status has emerged as a negative predictor of clinical benefit from anti-EGFR antibodies in colorectal cancer, and anti-EGFR antibodies use was limited to KRAS wild type tumors." (PMID 23935912, 2013). "In the LARC population studied here, the observed frequencies of tumor aberrations of KRAS, BRAF, PIK3CA, and ERBB2 were in the order of magnitude previously reported in colorectal cancer." (PMID 23226389, 2012). "To further confirm these results, we used two colorectal carcinoma cell lines (CHD-1 and HDC-9) with yet unknown mutation status that have been established by our work group in the 1990s and found that the cell line overexpressing Abi1 (CHD-1) carries an activating mutation in codon 13 of KRAS." (PMID 22808230, 2012). "However, the benefits of anti-EGFR monoclonal antibody treatment of advanced colorectal cancer may be limited to patients without KRAS mutations." (PMID 21407216, 2011). "Gene copy number (GCN) of EGFR and KRAS status predict response and outcome in patients treated with anti-EGFR therapy, but their prognostic significance in colorectal cancer patients is still unclear." (PMID 20842128, 2010). "Epidermal growth factor receptor inhibitor therapy is now approved for treatment of metastatic colorectal carcinomas (CRC) in patients with tumors lacking KRAS mutations." (PMID 21122130, 2010). "However, unlike with lung cancer (EGFR gene amplification, EGFR gene mutation, lack of KRAS mutation) and colorectal cancers (lack of KRAS mutations), molecular markers of sensitivity to EGFR blockade are currently unknown for gastroesophageal carcinomas." (PMID 19636422, 2009). "In this article, we will discuss targeted therapies for colorectal cancers (CRC) based on EGFR signaling pathway and review published data about the potential usefulness of KRAS as a biological marker for response to these therapies." (PMID 19386128, 2009). "The involvement of FOXO1 in colorectal cancers and KRAS-induced metabolic reprogramming is not well-characterised." (PMID 41266617, 2026). "For example, patients with KRAS mutations are known not to respond well to EGFR (Epidermal Growth Factor Receptor) inhibitors, which are often used in colorectal cancer therapy." (PMID 40083375, 2025). "Similarly, CXCL3 is upregulated due to KRAS-mediated inhibition of interferon regulatory factor 2 (IRF2), which exacerbates the recruitment of MDSCs in colorectal cancer." (PMID 40303413, 2025). "KRAS inhibitors (e.g., sotorasib and adagrasib) in combination with the EGFR antibody have been proved more effective than either agent alone in patients with colorectal cancer." (PMID 40304209, 2025). "In colorectal cancer, TRIM21-mediated K63 ubiquitination reduces the stability of the hnRNPA2B1 protein, leading to a decline in nuclear export and translation of KRAS mRNA, and reduced activation of the MAPK signaling pathway, ultimately inhibiting the malignant progression of colorectal cancer." (PMID 40379610, 2025). "As for colorectal cancer (CRC), there were significant differences in the intratumoral microbiota between tissues with and without KRAS mutation or microsatellite instability (two key factors underlying CRC progression and prognosis)." (PMID 40185720, 2025). "KRAS-mediated repression of interferon regulatory factor 2 (IRF2) results in high expression of CXCL3, which binds to CXCR2 on myeloid-derived suppressor cells (MDSCs) and regulates the immune responses in colorectal cancers." (PMID 40547026, 2025).
colorectal cancer (continued). "KRAS G12C inhibitors, including sotorasib and adagrasib, have revolutionized the treatment landscape for certain malignancies, particularly non–small cell lung cancer (NSCLC) and colorectal cancer (CRC), where they have received FDA approval." (PMID 41355935, 2025). "As it is essential to consider ITH during preclinical development of anticancer therapeutics, we chose a panel of colorectal cancer PDOs spanning genetic (e.g., MSI/MSS and KRAS/BRAF /APC status), clinical stage, anatomic location, chemosensitivity, and CSC composition." (PMID 40882026, 2025). "Molecular targeted therapies targeting KRAS signaling have significantly improved patient outcomes, but they have not achieved sufficient therapeutic efficacy in colorectal cancer (CRC)." (PMID 41455700, 2025). "Overall, for patients with colorectal cancer, the impact of KRAS mutations on survival is not fully clear—certainly, those with KRAS mutations on codon 12 have worse outcomes, but those with codon 13 mutations may have similar outcomes to patients with wild-type KRAS." (PMID 39001441, 2024). "For instance, SMAD4 loss alone may not initiate tumor formation but can promote tumor progression initiated by other genes, such as KRAS activation in pancreatic ductal adenocarcinoma and APC inactivation in colorectal cancer." (PMID 38666907, 2024). "This test confirmed the absence of residual colorectal cancer cells resistant to the encorafenib and cetuximab with KRAS Q61H." (PMID 38962037, 2024). "Finally, phase I/II clinical trials are currently ongoing to evaluate the therapeutic potential of a KRAS-targeting mRNA vaccine, ELI-002 against operable colorectal cancer." (PMID 39654897, 2024). "Downregulation of KRAS enhanced the ability of ectopic IL24 to suppress proliferation and induce apoptosis in mutant KRAS colorectal cancer cells but not in wild‐type KRAS cells." (PMID 38414326, 2024). "EGFR signaling was identified as the dominant mechanism of resistance to KRAS G12C inhibitors in colorectal cancer rather than in non–small cell lung cancer." (PMID 39704172, 2024). "However, the KRAS gene is frequently mutated in a variety of human cancers, especially non–small cell lung cancer (NSCLC), colorectal cancer, and pancreatic ductal adenocarcinoma (PDAC), resulting in the oncogenic activation of the KRAS protein." (PMID 39661665, 2024). "Importantly this also extended to larger tumor indications, such as lung, pancreatic and colorectal cancer, in combination with RTK, KRAS-mutant selective and MAPK inhibitors, leading to more efficacious and durable responses." (PMID 38565920, 2024). "However, in colorectal cancer (CRC), resistance to KRAS-targeted therapy develops rapidly, making it imperative to understand its underlying mechanisms." (PMID 39061234, 2024). "Patritumab deruxtecan also demonstrated preclinical efficacy in colorectal cancer xenografts, showing a dependence on HER3 expression rather than on KRAS mutations." (PMID 39651731, 2024). "Accordingly, we tested the effect of sotorasib and adagrasib in combination with both farnesyl-transferase inhibitors (tipifarnib, lonafarnib) on the KRAS-G12C mutant pancreatic cancer cell line MIAPACA2 and a novel patient-derived colorectal cancer cell line PF97." (PMID 38278976, 2024). "Response to single agent KRAS G12C inhibition in NSCLC, colorectal cancer and pancreatic cancer." (PMID 38576709, 2024). "Researchers have discovered many genes related to the occurrence and development of colorectal cancer through genomic studies, including but not limited to the PIK3CA, KRAS, APC, SMAD4, and BRAF genes, among which the PIK3CA gene has attracted widespread attention." (PMID 39555098, 2024). "Furthermore, small-molecule inhibitors of ERK either show no efficacy or produce a partial clinical response in patients with KRAS- and BRAF-mutant colorectal cancer." (PMID 38277448, 2024).